NRAS (NRAS proto-oncogene, GTPase)
Diseases named in the same sentence as NRAS in open-access papers (continued):
Sharing a sentence is not in itself a finding about the gene and the disease.
acute myeloid leukemia (continued). "The mutational spectrum and prognostic factors of NRAS-mutated (NRASmut) acute myeloid leukemia (AML) are largely unknown." (PMID 32699322, 2020). "Genes associated with the pathogenesis of acute myeloid leukemia, such as DNMT3A, NRAS, RUNX1, EZH2, and KRAS, were more commonly mutated in the hypermethylation group." (PMID 30635552, 2019). "Somatic mutations that lead to constitutive activation of NRAS and KRAS proto-oncogenes are among the most common in human cancer and frequently occur in acute myeloid leukemia (AML)." (PMID 27991934, 2017). "12% to 19% of acute myeloid leukemia patients carry a gain-of-function mutation within the RAS genes, while NRAS is most frequently affected." (PMID 25901794, 2015). "Recently, the differential compartmentalization of Bcl2 and NRAS has been reported to influence disease states, such as myelodysplastic syndromes and acute myeloid leukemia." (PMID 22069448, 2011). "Finally, we found that OAS3 was observably related with some mutation types (CEBPA, FLT3 internal tandem duplication, NRAS, and EVI1 expression) in patients with acute myeloid leukemia (LAML)." (PMID 41700140, 2026). "N-Ras palmitoylation by the DHHC family of palmitoyl acyl transferases (PATs) and depalmitoylation by ABHD17 serine hydrolases is a dynamic process that is essential for the growth of acute myeloid leukemias (AMLs) harboring oncogenic NRAS mutations." (PMID 40166265, 2025). "Acute myeloid leukemia (AML) arises from the clonal expansion of aberrant hematopoietic stem cells, for which early events like CH-associated mutations together with later events like FLT3-ITD, NRAS or NPM1 mutations initiate the disease." (PMID 37880479, 2024). "Mutations in the RAS/MAPK signaling pathway are recurrent in acute myeloid leukemia (AML), primarily involving NRAS and KRAS." (PMID 42297916, 2026). "Although RAS/MAPK pathway mutations affecting NRAS, KRAS, and/or PTPN11 are common in de novo or acute myeloid leukemia (AML)-myelodysplasia-related (MR), BRAF variants rarely occur in AML." (PMID 39596583, 2024). "Apart from FLT3, there are some other recurrent genetic alterations that are also found in other acute myeloid leukemia subtypes, including WT1 (14%), NRAS (10%), KRAS (4%) and MYC amplification (12%)." (PMID 38921185, 2024). "The study utilized aggressive murine myeloid leukemia models driven by retroviral transduction of oncogenes: MLL-AF9 and NRAS G12V-driven acute myeloid leukemia (AML) and BCR-ABL and NUP98-HOXA9-driven blast crisis of chronic myelogenous leukemia (CML-BC) models." (PMID 38017534, 2023). "Mutations in the KRAS and NRAS genes are frequently identified, with mutations in NRAS more frequent than mutations in KRAS, in myeloid disorders (15%–60%), including acute myeloid leukemia (AML), atypical chronic myeloid leukemia (aCML), CMML, and JMML." (PMID 37317963, 2023). "A 2018 study focusing on Wogonoside—a flavonoid extracted from Scutellaria baicalensis Georgi with antileukemic properties—reported that Wogonoside inactivates the NRAS/RAF1 signaling pathway by blocking NRAS palmitoylation in acute myeloid leukemia (AML) cells." (PMID 36018061, 2023). "WT1, KRAS, NRAS mutations, FLT3 activation, or Myc trisomy, which are common genetic events in many other subsets of acute myeloid leukemia (AML), may be observed in APL patients." (PMID 29795382, 2018).
acute myeloid leukemia (continued). "Three miRNA target genes also include NRAS, RUNX1, MAPK1, which are precisely enriched in acute myeloid leukemia pathway." (PMID 28473658, 2017). "HRAS mutations are thus rarely found in myeloid malignancies, whereas mutations leading to oncogenic KRAS or NRAS activation occur in ~ 40% of cases with chronic myelomonocytic leukemia and in 20% of cases of monocytic (FAB classes M4 and M5) forms of acute myeloid leukemia (AML)." (PMID 30323311, 2019). "In acute myeloid leukemia (AML), depletion of RALB was shown to phenocopy loss of NRAS(V12), while loss of AKT or MAPK did not." (PMID 35626682, 2022). "Notably, in acute myeloid leukemia (AML) cells KRAS, neuroblastoma RAS viral oncogene homolog (NRAS) and ERK2 have been identified as direct targets of miR-181a." (PMID 30081513, 2018).
colon carcinoma (69 papers, 2009 to 2025). "In a multivariate analysis, we identified male sex, age ≥50, colon tumors, early-stage tumors, NRAS mutant tumors, and BRAF wild-type tumors as risk factors for CRC patients with high-risk polyps." (PMID 38978992, 2024). "The current findings suggest that male gender, age ≥50, colon tumors, early-stage tumors, NRAS mutant tumors, and BRAF wild-type tumors are risk factors for CRC with high-risk polyps." (PMID 38978992, 2024). "Clinicopathological characteristics according to KRAS and NRAS mutations status in 210 colon cancer patient." (PMID 33784337, 2021). "The results showed that KRAS/NRAS/BRAF mutation rates in colon cancer were 44.2, 1.2, and 3.5%; in rectal cancer were 37.1, 4.3, and 0.7%; in gastric cancer were none, none and 2.9%." (PMID 30416987, 2018). "In particular, KRAS is the isoform prevalently mutated in pancreas, lung and colon cancer, while NRAS is the predominant isoform mutated in cutaneous melanomas and acute myelogenous leukemia and HRAS is the predominant isoform mutated in the bladder." (PMID 29534749, 2018). "A recent study on Chinese patients showed that among KRAS, BRAF, PIK3CA and NRAS mutations in stage II to III colon cancers (n = 228), only PIK3CA mutations were an independent prognostic biomarker for poor OS among stage III patients." (PMID 29666387, 2018). "We observed many KRAS (52.9%), PIK3CA (12.4%), and NRAS (7.4%) mutations in a colon cancer tissue collection (N = 121)." (PMID 24658394, 2014). "In a study of colon cancer xenografts, there was concordance between gene copy number and mutation (NRAS, KRAS, BRAF, PIK3CA) in first- and second-generation xenografts and in the parent tumor." (PMID 23981300, 2013). "Moreover, the NRAS-mutated group comprised only 3 patients, reflecting the sparse prevalence of NRAS-mutated colon cancers (3–5%)." (PMID 36136880, 2022). "Our study aimed to estimated the incidence of KRAS and NRAS mutations (KRAS exons 2/3/4 and NRAS exons 2/3/4) in Moroccan population, to identify the clinicopathological characteristics of KRAS and NRAS gene mutations and to evaluate their prognosis value in colon cancer." (PMID 33784337, 2021). "NRAS mutations were detected in 1 out of 86 (1.2%) colon cancer samples." (PMID 30416987, 2018). "A NRAS mutation (N = 1) was observed in a case of left colon cancer." (PMID 26909603, 2016). "Considering rare data provided for NRAS mutations in stage II/III colon cancer, large population cohort investigation for this gene mutation detection should be performed, as NRAS closely related to KRAS and NRAS mutation was prognostic for EGFR MoAbs therapy inmCRC28." (PMID 27074743, 2016). "NRAS mutations had an overall incidence of 3.4% (3/87) in HER2-amplified CRC, occurring at comparable, low rates in HER2-amplified colon cancer (3.3%, 2/61) and rectal cancer (3.8%, 1/26)." (PMID 40742050, 2025). "Male gender, advanced age, colon tumors, early-stage tumors, NRAS mutant tumors, and BRAF wild-type tumors were identified as characteristics associated with CRC complicated by high-risk polyps." (PMID 38978992, 2024). "In the univariate analysis, male sex, age ≥50, colon tumors, early-stage tumors, NRAS mutant tumors, and BRAF wild-type tumors were significantly associated with an increased risk of high-risk polyps." (PMID 38978992, 2024). "The remaining patients were patients with right or left colon tumors and we compared the OS, molecular mutations (KRAS, NRAS, BRAF, MSI status), and clinicopathological features of our patients with transverse colon tumors with these patients." (PMID 39629291, 2024). "This systematic review focuses on the prognostic significance of KRAS, NRAS, and BRAF mutations within MSI-H colon cancer." (PMID 38786299, 2024). "Our findings confirm the complex interplay between genetic mutations and MSI status, emphasizing the nuanced role of MSI in modifying the prognostic implications of KRAS, NRAS, and BRAF mutations in colon cancer." (PMID 38786299, 2024).
colon carcinoma (continued). "This is exemplified by resistance to anti-EGFR therapies in colon cancer, which can be mediated by downstream KRAS- or NRAS-activating mutations." (PMID 35625759, 2022). "Both uterine cancer and colonic cancer samples were examined for the presence of somatic mutations in the KRAS and NRAS genes in order to determine the clonality of the development of malignant neoplasms." (PMID 33937060, 2021). "The selected 299 mutations cover the National Comprehensive Cancer Network (NCCN) guideline of colon cancer recommended gene list relevant to treatment and prognosis, such as KRAS, NRAS, BRAF V600E mutations." (PMID 33008377, 2020). "When analyzing the mutation rates of KRAS, NRAS, and BRAF in different locations, it can be found that KRAS gene mutation rate was significantly different in colon cancers (44.2%), rectal cancers (37.1%) and gastric cancers (0%) (p < 0.001)." (PMID 30416987, 2018). "To answer this question, we tested the effects of Gamitrinib and 6-thio-dG in KRAS-mutant lung and colon cancer cell lines as well as NRAS-mutant glioblastoma cells." (PMID 29695835, 2018). "The three human RAS genes (KRAS, NRAS and HRAS) are the most frequently mutated oncogenes in human cancer appearing in 90% of pancreatic, 35% of lung and in 45% of colon cancers." (PMID 29534749, 2018). "Compared with colon cancer and rectal cancer, KRAS and NRAS have a lower mutation rate in gastric cancer." (PMID 30416987, 2018). "In this retrospective study, we evaluated common hot spot gene mutations located downstream of EGFR signaling pathway, the potential prognostic value for KRAS, BRAF, PIK3CA and NRAS was assessed in 228 stage II-III colon cancer." (PMID 27074743, 2016). "APC mutations were associated with poor prognosis in (5-fluorouracil treated) stage III colon cancers (p = 0.005; HR = 4.1), an effect that was further enhanced by mutations in MAPK pathway (KRAS, NRAS, BRAF) genes." (PMID 27729614, 2016). "In vitro, VEGF-A induced a resistance toward cetuximab cytotoxicity on three KRAS and NRAS wild type colon cancer cell lines in a VEGFR2 and Stat-3-dependent manner." (PMID 26824184, 2016). "Similar results have been demonstrated in primary colon cancers, showing that the CT based-radiomics signature was significantly associated with KRAS/NRAS/BRAF mutations and this approach may be useful for analysis of tumor genotype." (PMID 39329997, 2024). "KRAS and NRAS mutations were observed exclusively in non-CDX2-suppressed colon cancers, with no cases in the CDX2-suppressed group bearing such mutations." (PMID 39452477, 2024). "This impact on chemotherapy response can influence the prognosis and treatment options for patients with non-metastatic colon cancer harboring NRAS mutations, but its role in MSI patients still needs to be defined." (PMID 38786299, 2024). "Consequently, we identified male sex, age ≥50, colon tumors, early-stage tumors, NRAS mutant tumors, and BRAF wild-type tumors as independent risk factors for synchronous high-risk polyps." (PMID 38978992, 2024). "The remaining patients were patients with right or left colon tumors and we compared the overall survival (OS), molecular mutations (KRAS, NRAS, BRAF, MSI status), and clinicopathological features of our patients with transverse colon tumors with these patients." (PMID 39629291, 2024). "In many studies, KRAS mutation incidence was higher in right-sided than in left-sided colon tumors and higher in women but not for NRAS mutation." (PMID 37277698, 2023). "When considered together, the absence of NRAS type mutations was associated with left colon tumors RR2 = 1.515 (95% C1 = [1.242, 1.849])." (PMID 35681771, 2022). "Likewise, NRAS-Q61K and NRAS-Q61R mutations in skin and blood cancers; PIK3CA-E545K and PIK3CA-H1047R mutations in breast, lung, and colon cancers; and the C-Kit-D816V mutation in blood cancer are reported to commonly and frequently occur." (PMID 30813491, 2019).
colon carcinoma (continued). "KRAS/NRAS/BRAF mutations were not significantly related to patients' age analyzed by Student's t-test or gender analyzed by Chi-square test in colon cancer." (PMID 30416987, 2018). "In this study, we investigated the mutation status of KRAS (exons 2, codon 12/13), NRAS (exons 2/3/4, codon 12/13/59/61/117/146) and BRAF (exons 15, codon 600) in 260 patients, including 86 cases of colon cancer, 140 cases of rectal cancer and 34 cases of gastric cancer." (PMID 30416987, 2018). "Although our results demonstrated that among left-sided colon cancer patients, those with early recurrence were more likely to carry PIK3CA and NRAS mutations than those with late recurrence, the number of patients was small, and selection bias might have occurred." (PMID 33919924, 2021). "In addition, the current study did not consider the KRAS/NRAS/BRAF mutation statuses in colon cancer cells which are important for clinical outcomes and survival in cancer patients." (PMID 29732005, 2018). "The mutation status of KRAS (exons 2, codon 12/13), NRAS (exons 2/3/4, codon 12/13/59/61/117/146) and BRAF (exons 15, codon 600) were detected by amplification refractory mutation system polymerase chain reaction (ARMS-PCR) in 86 colon cancer, 140 rectal cancer and 34 gastric cancer tissues." (PMID 30416987, 2018). "However, whether mutations in KRAS together with downstream factors BRAF, PIK3CA and NRAS impact prognosis is still unclear for stage II-III colon cancer." (PMID 27074743, 2016). "There was a significant difference in the expression of BRAF between the BRAF (V600E) MT and WT (p = 0.008) in colon cancers; and there was a significant difference in the expression of EGFR between the NRAS MT and WT (p = 0.021) in rectal cancers." (PMID 30416987, 2018). "This systematic review aims to investigate how the presence of NRAS, KRAS, or BRAF mutation in non-metastatic MSI colon cancer patients affects outcomes such as DFS, OS, and survival after recurrence (SAR)." (PMID 38786299, 2024). "This systematic review synthesizes a comprehensive range of studies examining the prognostic significance of NRAS, KRAS, and BRAF mutations within non-metastatic MSI colon cancer." (PMID 38786299, 2024). "KRAS, NRAS, BRAF, HER2, and MSI must be evaluated in all patients with advanced colon cancer." (PMID 34541365, 2021). "In maximal settings, for patients with left-sided colon cancer and known KRAS/NRAS wild type (WT) molecular status, anti-EGFR antibodies such as cetuximab or panitumumab may be added to chemotherapy doublet, with a moderate-strength recommendation." (PMID 32150483, 2020). "On the contrary, the five remaining colon cancer cell lines, namely SW48, DIFI, MICOL24, CACO-2 and E705, showed no hyperactivating mutations in KRAS, NRAS, BRAF and PIK3CA genes, with the E705 cell line carrying a silent mutation in PIK3CA gene." (PMID 33233823, 2020). "Compared with colon cancer rectal cancer, KRAS/NRAS/BRAF have a lower mutation rate in gastric cancer, furthermore, there is no consistent conclusion on the role of KRAS/NRAS/BRAF mutations in gastric cancer." (PMID 30416987, 2018). "KRAS, BRAF and NRAS mutations do not have major prognostic value in stage II and III colon cancer, subtypes of gene mutations should be further investigated for a better understanding in CRC." (PMID 27074743, 2016). "We reviewed the previous literatures with keywords “colon cancer,” “KRAS,” “NRAS,” and “BRAF,” and there was no agreed conclusion of the driver gene’s role in CRC patients." (PMID 36862900, 2023).